CD14 (CD14 molecule)
Diseases named in the same sentence as CD14 in open-access papers (continued):
Sharing a sentence is not in itself a finding about the gene and the disease.
systemic lupus erythematosus (48 papers, 2013 to 2025). An autoimmune multi-organ disease typically associated with vasculopathy and autoantibody production. "Increased CD14+ DC3 levels are associated with heightened disease activity in systemic lupus erythematosus." (PMID 40584260, 2025). "Emerging evidence has also highlighted the existence of a novel inflammatory subset of cDC2s which are CD5−CD163+CD14+ and has implicated their expansion in systemic lupus erythematosus." (PMID 33205448, 2021). "One study revealed that CD163+CD14+ DC3s were significantly increased within the CD5− DC subset exclusively in systemic lupus erythematosus (SLE) patients which correlated with disease severity." (PMID 40584260, 2025). "Together, these findings identify a disease-specific expansion of type I interferon–producing myeloid subsets in photosensitive dermatoses: pDCs in CLE producing IFN-α and CD14+ MC cells in DM, and to a lesser extent in lupus, producing IFN-β." (PMID 40894544, 2025). "The subsequent studies phenotypically characterized the DC3 population as CD163+CD14+ DCs that accumulate in the blood of patients with systemic lupus erythematosus (SLE)." (PMID 37520521, 2023). "In a very recent study of CD14+ monocytes from systemic lupus erythematosus patients, it was reported that there was an emergence of an immunosuppressive M2-phenotype upon TLR-induced epigenetic activation of PPARG expression." (PMID 37254181, 2023). "To verify the effect of RNASE2 on IL-10 secretion, we isolated CD14+ monocytes from lupus PBMCs by magnetic beads and cultured with RNASE2 siRNA." (PMID 35265065, 2022). "Differential expression of CD163 and CD14 marks different stages of maturation and activation in DC3, and an increased frequency of CD163+ CD14+ blood DC3 with proinflammatory function exists in patients with active systemic lupus erythematosus (SLE)." (PMID 34614036, 2021). "Gene set enrichment analyses (GSEA) on differentially expressed genes based on SLICC score, SLEDAI score, lupus severity index, and lupus nephritis showed an elevated expression of interferon pathways in the CD14+ monocytes." (PMID 33883687, 2021). "On the other hand, the presence of CD163+CD14+ infDCs in the patients with circulation of lupus suggests that infDC from the peripheral circulation enter the kidney in LN." (PMID 33659005, 2021). "LILRA3 levels in blood serum and CD14+ monocytes enhanced in systemic lupus erythematosus and resulted in disease severity." (PMID 33953859, 2021). "We observed increased proportions of non-classic monocytes, decreased proportions of classic monocytes, elevated levels of plasma sCD14 as well as reduced surface expression of CD14 on monocytes comparing women to men and lupus patients to controls." (PMID 25485543, 2014). "We used whole exome sequencing to genetically map the associated mutations and performed transcriptome profiling and enrichment analysis in CD14+ monocytes of the patient and immune phenotyping by mass cytometry (CyToF), comparing to healthy individuals and lupus patients as disease controls." (PMID 39871364, 2025). "HVEM expression was also reduced in CD8+ T cells and CD14+ monocytes from patients with lupus." (PMID 39688922, 2024). "Our previous study showed that CD14+CD16+ monocytes in patients with systemic lupus erythematosus showed inflammatory phenotype, with increased CD80, CD86, HLA-DR, and CX3CR1, which could promote Th17 response." (PMID 32958023, 2020). "Moreover, analysis of TAM receptor expression in patients suffering from systemic lupus erythematosus (SLE) has convincingly indicated increased expression of Mer on CD14++CD16+ intermediate monocytes." (PMID 30619243, 2018). "Indeed, although at present we cannot decipher the cells of origin of circulating miR-148a or miR-21-5p, a previously published study revealed that an increased expression of miR-148a occurred in CD14+ osteoclasts precursor cells derived from lupus patients." (PMID 30486455, 2018).
systemic lupus erythematosus (continued). "Peripheral blood was collected from two healthy persons and two patients with systemic lupus erythematosus (SLE), and CD14+ monocytes were selected to perform Hi-C, RNA-seq, ATAC-seq and ChIP-seq analyses." (PMID 35309301, 2022). "Lupus-like symptoms with monocytosis reminded us of Ras-associated autoimmune leukoproliferative disorder, and Sanger sequencing of KRAS and NRAS genes from the patients’ peripheral blood mononuclear cells (PBMC), sorted CD3+ lymphocytes and CD14+ monocytes, and cerebrospinal fluid were performed." (PMID 35361277, 2022). "CD14+ monocytes from patients with autoimmunological systemic lupus erythematosus (SLE) have decreased HO-1 expression both at mRNA and protein level." (PMID 33787980, 2021). "They revealed high heterogeneity of myeloid cells with expansion of a specific cDC2 subset characterized by expression of CD163 and CD14 and correlating with systemic lupus erythematosus (SLE) progression." (PMID 32849606, 2020). "In the lupus dataset, CELLECTION consistently upweighted CD14+ monocytes cells as predictive of disease status." (PMID 40950226, 2025). "Recently, it was demonstrated that in systemic lupus erythematosus (SLE) patients, interferon-regulated genes are hypomethylated in naïve CD4+ T cells, CD19+ B lymphocytes, and CD14+ monocytes." (PMID 36429769, 2022). "A circulating CD1c+CD14+CD163+ cDC2 subset, related to the DC3s, was found to expand correlatively with disease activity in patients with systemic lupus erythematosus (SLE)." (PMID 34566965, 2021). "In TN-JDM, we observed a skewing of both CD16+ and CD14+ monocytes toward an inflammatory and antigen-presenting state, co-expressing IFN and IL-1 axis genes, consistent with a finding recently described in childhood lupus." (PMID 35799782, 2022). "In addition, the most inflammatory CD14+ DC3 subset, namely CD163+CD14+ DC3, increase in the blood of patients with systemic lupus erythematosus." (PMID 32256490, 2020). "Interestingly, CD40L+/CD14+ peripherally circulating monocytes and CD40L+ T cells have been reported in active systemic lupus erythematosus." (PMID 33021986, 2020). "They further showed that CD14+ PBMCs from lupus patients possessed elevated miR‐148a levels and enhanced osteoclastogenesis capacity, which may contribute to the lower BMD in lupus patients compared with normal controls." (PMID 31667459, 2019). "According to different analyses of CpG methylation, including CD4+ T-cells, CD19+ B-cells, and CD14+ monocytes, done in various immune cell types of several SLE patients, it can be assumed that lupus patients exhibit more global DNA hypomethylation in CD4+ T-cell." (PMID 29803202, 2018). "Mer expression in monocytes from lupus patient blood followed the same pattern as in monocytes from healthy individuals, with highest expression in the CD14++CD16+ populations and lowest in the CD14++CD16- populations." (PMID 24650765, 2014).
leukemia (45 papers, 2006 to 2025). A malignant (clonal) hematologic disorder, involving hematopoietic stem cells and characterized by the presence of primitive or atypical myeloid or lymphoid cells in the bone marrow and the blood. "Further studies are necessary to elucidate the role of the TLR1, TLR4, TLR5, TLR6, TLR9, and CD14 polymorphisms in the pathogenesis of leukemia." (PMID 36071076, 2022). "Exposure of MLL-rearranged leukemia cells to this compound caused cell cycle arrest and promoted differentiation of those cells, both morphologically and by increased CD14 expression." (PMID 24858818, 2014). "Among responders, the proportion of CD14+ monocytes in leukemia cells increased after ICI treatment across all defined radial neighborhoods [rate ratio (RR) range: 2.5 to 2.7; adjusted P values <0.001]." (PMID 40632867, 2025). "Among responders, the proportion of CD14+ monocytes in leukemia cell increased after ICI treatment across all defined radial neighborhoods (rate ratio [RR] range 2.5–2.7, adjusted p-values < 0.001)." (PMID 39975227, 2025). "Knockdown of CNOT3 induced differentiation in leukemia cells evidenced by elevated expression of CD11b and CD14 cell surface markers and changes in cellular morphology and increased apoptosis." (PMID 38491013, 2024). "In spleen, GDYO treatment reduced spleen weight and number of blast cells and leukemia stem cells, while increased frequencies of CD11b/CD14 mature cells." (PMID 36163326, 2022). "Application of the platform to MUTZ3 leukemia cells revealed a marked reduction in cellular m6A levels as CD34+ leukemic progenitors differentiate to CD14+ myeloid cells." (PMID 34734208, 2021). "A previous study showed that CD11b and CD14 were relatively classic markers of differentiation in leukemia." (PMID 32296698, 2020). "A previous study showed that CD11b and CD14 were relatively classic markers of differentiation in leukaemia." (PMID 31943751, 2020). "Similar to our results, several studies showed that ATRA increases CD14 expression in human monocyte-like U937 cells and promyelocytic leukemia cell line NB4." (PMID 31950055, 2019). "In all five primary AML samples, mebendazole treatment induced significant differentiation in the leukemia blasts as evidenced by increased expression of myeloid markers (CD11b, CD11c, and CD14)." (PMID 31727951, 2019). "Tp92 mediated the human monocytic cell line derived from an acute monicytic leukemia patient (THP‐1) cell death by recognizing CD14 and/or TLR2 on cell surfaces." (PMID 30596396, 2018). "In chronic lymphocytic leukemia, CD14-positive monocytes can differentiate into nurse-like cells (NLCs) that provide a critical tumor-promotional and -protective microenvironment for the leukemia." (PMID 29872489, 2018). "H7 treatment also increased reactive oxygen species (ROS) level and cell differentiation in leukemia cells, as reflected by the upregulation of the cell surface differentiation marker CD11b/CD14 and the morphological maturation of cells." (PMID 26716647, 2016). "Eight genes (BAALC, CD14, CD34, CD74, DNTT, HLA-DRA, IRF8, and MN1) were all associated with “leukemia” (P = 1.15 × 10−4), “acute myeloid leukemia” (P = 9.37 × 10−3), and “proliferation of myeloid cells” (P = 0.044)." (PMID 26517675, 2015). "To evaluate the potential of tetrandrine to induce NB4 leukemia cell differentiation, we examined CD14 and CD11b expression on the cell surface." (PMID 25797266, 2015). "Acute myeloid leukaemia patients with hypermethylation of any SFRP gene as a whole had higher frequency of CD19 (P=0.0004), CD7 (P=0.0144), and CD34 expression (P=0.012), but had lower frequency of CD14 expression (P=0.0395) on the leukaemia cells." (PMID 22095226, 2011). "Alternatively, this observation may reflect treatment-induced maturation of leukemia cells into CD14+ monocytes." (PMID 40632867, 2025).
leukemia (continued). "Furthermore, HSC-prog cells showed more interactions with other cells through known ligand–receptor pairs, such as leukaemia-associated ligands CXCL2, CXCL3, and FLT3, signalling to the receptors CXCR1 and CXCR2 expressed by CD14-mono and NK cells." (PMID 37615858, 2024). "THP-1 is a human leukemia-derived monocyte cell line that is CD14-positive and CD16-negative." (PMID 39845969, 2024). "Finally, pre-treatment with GDYO profoundly mitigated both the frequencies and absolute numbers of leukemia blasts and leukemia stem cells, while elevating CD11b+/CD14+ matured cells in both BM and spleen." (PMID 36163326, 2022). "This could mean that CD14+ cells could produce EVs, that could mediate various reaction in leukemia and healthy samples." (PMID 35477770, 2022). "RT1(9a) Kit+Sca1−/lowCD34− AML cells exhibited variable combinations of FcgR, CD48, and CD14, suggesting that leukemias may have developed from different subclones within that compartment." (PMID 35921412, 2022). "Moreover, using a human leukemia model, IL-34 enhanced the differentiation of leukemia cells into differentiated macrophages by means of an increase in CD14 or CD68 and a decrease in CD71, a cell surface marker for immature myeloid cells." (PMID 33408768, 2021). "H7 treatment also induced cell differentiation in U937, in HL60, in some primary leukemia cells, and slightly in CBMNCs and BMMNCs, as shown by the increased CD11b and CD14 expression and/or by the morphological changes in cells." (PMID 26716647, 2016). "Adventitial monocyte binding to AngII‐infused aorta in vitro was dependent on CD14, and incubation of human acute monocytic leukemia cell line‐1 (THP‐1) monocytes with IL‐6 or conditioned medium from perivascular adipose tissue (PVAT) upregulated CD14 expression." (PMID 23537804, 2013). "Mass cytometry further revealed that YW3-56 treatment simultaneously suppresses leukemia stemness (CD44/CD133 downregulation) and promotes myeloid differentiation (CD11b/CD14 upregulation), as well as enhances immunogenic activation (CD80/CD86 increase)." (PMID 41304891, 2025). "This suggested that there was an overall increase in CD14+ monocytes post ICI therapy for responders, irrespective to leukemia cell proximity." (PMID 39975227, 2025). "We used CD14 as a marker of myeloid differentiation and CD33 as a marker for immature and aggressive leukemia to characterize our CRISPR/Cas9 MLL-AF4 and MLL-AF9 cells before and following treatment with CAD204520." (PMID 37833915, 2023). "We observed that there were fewer granzyme K+ CD8+ T effector cells and CD14+ monocytes in leukemia cell neighborhoods in responders than in nonresponders at baseline." (PMID 39975227, 2025). "To prove whether TNFAIP2 can induce the differentiation of monocytic leukaemia cells, we transduced MOLM-13 cells with the TNFAIP2 overexpression (TNFAIP2-OE) construct and observed the expression of CD11b and CD14." (PMID 38271140, 2024). "In this study, we used the widely characterized U87MG human GBM cell line and CD14+ human primary monocytes, or the THP-1 human leukemia monocytic cell line to evaluate the impact of soluble factors as well as cell-to-cell dependent signaling on the behavior of both the GBM cells and the monocytes." (PMID 34065977, 2021). "Dramatic increases in differentiation markers CD11b and CD14 and prominently lobulated karyotypes were observed in GFP+ cell population from sh-LAMP5-AS1-transfected mice, implying that LAMP5-AS1 is necessary to inhibit differentiation in MLL leukemia cells." (PMID 32552847, 2020). "Indeed, we observed a significant mebendazole-induced differentiation in two AML leukemia cell lines (HL-60 and THP-1) based on NBT staining, flow cytometric analysis of the myeloid marker CD11b and CD14, and Wright’s staining." (PMID 31727951, 2019).
leukemia (continued). "Since tumor-associated factors induce the differentiation of monocytes or BDCA1+ DCs into BDCA1+CD14+ cells, we hypothesized that BDCA1+CD14+ cells are also present in other cancers, such as leukemia." (PMID 30235890, 2018). "When the K562 cells were treated with the two drugs, no significant induction of CD11b or CD14 expression (typical markers of myelomonocytic differentiation of leukemia cells) was observed." (PMID 24959230, 2014). "This showed that there was an overall increase in CD14+ monocytes post-ICI therapy for responders, irrespective of leukemia cell proximity." (PMID 40632867, 2025). "In contrast, we see no binding with cervical carcinoma, several human leukemias, CD4 and CD14 subpopulations nor with human neutrophils." (PMID 16504122, 2006).
HIV-1 infection (44 papers, 2006 to 2025). The type species of lentivirus and the etiologic agent of acquired immunodeficiency syndrome (AIDS). "CD14+CD16+ cells were described as a subset of monocytes that is more susceptible to HIV-1 infection than CD16− cells, and they are an important source of the pro-inflammatory cytokine tumor necrosis factor (TNF)." (PMID 32849508, 2020). "We confirm in this study that Vpx interacts with SAMHD1 leading to ubiquitin-mediated degradation of SAMHD1, and renders CD14 positive monocytes susceptible to HIV-1 infection." (PMID 22174685, 2011). "Increased sialoadhesin expression on CD14+ monocytes occurred in response to HIV-1 infection with maximum expression associated with high viral load." (PMID 18414664, 2008). "We next assessed whether menopausal status alters the susceptibility of CD4+ T cells and CD14+ cells to HIV-1 infection in the FRT mucosa." (PMID 39872519, 2024). "In addition, previous studies have demonstrated that CD14+CD16+ cells are the predominant subset of monocytes in which HIV-1 infection is hosted, but the subset of monocytes associated with RR outcome in HIV-1 patients is unknown." (PMID 32849508, 2020). "We posit here that virion-incorporated CD14 is a potential contributor to the dysregulated immune responses present in the setting of HIV-1 infection." (PMID 38661384, 2024). "Data from other studies found that interleukin-6 [IL-6], C-reactive protein [hsCRP], soluble CD14 [sCD14], and D-dimer correlated with the overall mortality due to HIV-1 infection." (PMID 39205179, 2024). "The frequency of CCR5 editing exceeded 90% and bi-allelic CCR5 editing exceeded 70% resulting in significant inhibition of HIV-1 infection in primary human CD14+ monocytes." (PMID 39494910, 2024). "With untreated HIV-1 infection, the numbers of CD14+ cells in HIV-1-infected BLT mice were relatively stable, while the number of CD4+ cells declined with duration of replication consistent with replication-induced death of CD4+ cells." (PMID 37406092, 2023). "With untreated HIV-1 infection, the number of CD14+ cells was stable, but the number of CD4+ cells declined with time of infection." (PMID 37406092, 2023). "In fact, a pit assay showed that HIV-1 infection enhanced bone resorption activity of CD14-derived osteoclasts." (PMID 25809599, 2015). "We have shown the susceptibility of CD14-derived osteoclasts to HIV-1 and the enhancement of osteoclast differentiation and function by HIV-1 infection." (PMID 25809599, 2015). "In comparison, HIV-1 infection of T-cells co-cultured with SLAN DC depleted CD14− CD16+ monocytes, B-cells and pDC was similar to infection of CD4+ T cells alone." (PMID 26362311, 2015). "We examined expression of CD4, CXCR4, and CCR5, receptors for HIV-1 infection, in CD14-derived osteoclasts and macrophages." (PMID 25809599, 2015). "Phenotypical comparative studies demonstrate that CD14++CD16+ monocytes are more permissive to productive HIV-1 infection and harbor HIV-1 in infected individuals on cART as compare to the majority of blood monocytes (CD14++CD16−)." (PMID 25835530, 2015). "The proportion of inflammatory (CD14+CD16+) monocytes also tended to be higher in the setting of HIV-1 infection (median-14.8%) than among controls (median-13.9%), though not significantly (p = 0.19)." (PMID 26430882, 2015). "Soluble CD14 (sCD14) is a plasma marker of innate activation of monocytes and other CD14-expressing cells, and has been studied in particular in HIV-1 infection as a possible marker of microbial translocation over the intestinal barrier." (PMID 24130688, 2013). "More complexity in DC subsets and HIV-1 infection is evident in that dDC include a CD14+ subpopulation that appears permissive for productive HIV-1 infection." (PMID 24278768, 2013). "An important role for Siglec-1 in HIV-1 infection is in line with previous studies reporting increased expression of Siglec-1 on CD14+ monocytes and macrophages in HIV-1 infection." (PMID 23271952, 2012).